TRBV7-7 (T cell receptor beta variable 7-7)
Description:
V region of the variable domain of T cell receptor (TR) beta chain that participates in the antigen recognition. Alpha-beta T cell receptors are antigen specific receptors which are essential to the immune response and are present on the cell surface of T lymphocytes. Recognize peptide-major histocompatibility (MH) (pMH) complexes that are displayed by antigen presenting cells (APC), a prerequisite for efficient T cell adaptive immunity against pathogens. Binding of alpha-beta TR to pMH complex initiates TR-CD3 clustering on the cell surface and intracellular activation of LCK that phosphorylates the ITAM motifs of CD3G, CD3D, CD3E and CD247 enabling the recruitment of ZAP70. In turn ZAP70 phosphorylates LAT, which recruits numerous signaling molecules to form the LAT signalosome. The LAT signalosome propagates signal branching to three major signaling pathways, the calcium, the mitogen-activated protein kinase (MAPK) kinase and the nuclear factor NF-kappa-B (NF-kB) pathways, leading to the mobilization of transcription factors that are critical for gene expression and essential for T cell growth and differentiation. The T cell repertoire is generated in the thymus, by V-(D)-J rearrangement. This repertoire is then shaped by intrathymic selection events to generate a peripheral T cell pool of self-MH restricted, non-autoaggressive T cells. Post-thymic interaction of alpha-beta TR with the pMH complexes shapes TR structural and functional avidity.
Synonyms: TRBV77; TCRBV6S6A2T; TCRBV7S7
Gene: T-cell receptor variable (V) gene on chromosome 7 (142,511,626 to 142,512,127, forward strand). Ensembl gene ENSG00000253291.
Subcellular location: Cell membrane
Gene Ontology:
Biological process: cell surface receptor signaling pathway
Cellular component: plasma membrane
Homologues: Paralogues in human: TRBV7-6 (94% identical), TRBV7-4 (79% identical), TRBV7-9 (75% identical), TRBV7-2 (72% identical), TRBV7-3 (70% identical), TRBV7-1 (66% identical), TRBV11-1 (61% identical), TRBV11-2 (59% identical), TRBV11-3 (57% identical), TRBV12-4 (57% identical), TRBV12-3 (56% identical), TRBV12-5 (55% identical), and 39 more.